REST (RE1 silencing transcription factor)
Diseases named in the same sentence as REST in open-access papers (continued):
Sharing a sentence is not in itself a finding about the gene and the disease.
Stroke (14 papers, 2010 to 2025). Sudden impairment of blood flow to a part of the brain due to occlusion or rupture of an artery to the brain. "Therapeutically, lithium improved neurovascular remodeling by upregulating miR-124 expression, decreasing REST abundance and inhibiting deubiquitination of peri-infarct brain tissues and proteins on the 4th day post-stroke." (PMID 38515760, 2024). "HIF1A mRNA levels were augmented at 24 h after stroke as were levels of REST, a repressor of neuronal differentiation that was upregulated in the core and PI area at 24 h and 3 d after cerebral infarct." (PMID 23284893, 2012). "Similarly, miR-124 and REST provide therapeutic benefits in protecting against stroke via miR-124/USP14/REST, while other studies have demonstrated that lithium or M2 microglia-derived exosomes can regulate miR-124 and REST to play a neuroprotective role." (PMID 38515760, 2024). "Insults including trauma, stroke, infections, and long seizures (status epilepticus, SE) increase the nuclear expression and chromatin binding of the neuron-restrictive silencing factor/RE-1 silencing transcription factor (NRSF/REST)." (PMID 38641413, 2024). "Interestingly, while the NCX1 activators HIF-1 and Sp1 take part in neuroprotection, the NCX1 repressor factor REST worsens stroke-induced brain damage." (PMID 33931586, 2021). "miR-124 targets USP14 to suppresses deubiquitination of REST, which contributes to reduced brain injury and functional impairment, enhanced neurovascular remodeling, and increased angioneurogenesis 8 weeks post-stroke in mice with MCAO." (PMID 26041995, 2015). "Together, the data presented in this section suggest that the increases in REST induced by stroke or toxic treatments contribute to neuronal death by affecting the expression of numerous genes and their encoded proteins; whereas, other, non-death-inducing genes may be changed less or not at all." (PMID 26465007, 2015). "In the first stage, successive increases in REST mRNA and protein were found to occur in CA1 pyramidal neurons of organotypic hippocampal slice cultures 24-48 h after stroke." (PMID 26465007, 2015).
dementia (11 papers, 2014 to 2025). Loss of intellectual abilities interfering with an individual's social and occupational functions. "Decreased REST levels were correlated with higher oxidative stress and apoptotic events with dementia in AD brains compared with normal healthy brains." (PMID 34756885, 2021). "The same study showed that once this genetic network is dysregulated, REST is lost from the nucleus and presents in autophagosomes with pathological misfolded proteins in AD, frontotemporal dementia, and dementia with Lewy bodies." (PMID 34281203, 2021). "In AD and other dementias, REST is lost from the nucleus and is found with misfolded proteins in autophagosomes." (PMID 30819229, 2019). "REST is a master regulator of neuronal genes, whose protein abundance increases with stress and aging, but decreases with AD, frontotemporal dementia and dementia with Lewy bodies." (PMID 25187168, 2014). "Moreover, reduced NDEV levels of NRGN and REST with respect to controls were observed at both preclinical and dementia AD stages as well." (PMID 36155516, 2022). "In the AD patient population, all NDEV markers except P-S396-tau followed a common pattern of progressive increase with dementia severity that was significant for total tau, NRGN, and REST, but not for Aß42 and P-T181-tau." (PMID 36155516, 2022).
ischemia (11 papers, 2015 to 2023). A hypoperfusion of the BLOOD through an organ or tissue caused by a PATHOLOGIC CONSTRICTION or obstruction of its BLOOD VESSELS, or an absence of BLOOD CIRCULATION. "REST upregulation after MCAO-induced ischemia-reperfusion was also associated with a decrease in HCN1." (PMID 33813634, 2021). "Depletion of REST in vivo blocked ischemia-induced loss of miR-132 in hippocampal neurons, while overexpression of miR-132 in vitro and in vivo afforded robust protection against ischemia-induced neuronal death." (PMID 25821444, 2015). "Global ischemia induced REST expression to repress GluR2 and MOR-1, and REST knockdown protected neurons from ischemia-induced death." (PMID 37892159, 2023). "REST mRNA and protein increased after ischemia causing repression of GluR2 alongside Grin1 and other genes, while REST knockdown prevented GluR2 repression and rescued neurons from ischemia-induced death of hippocampal neurons in vivo." (PMID 33813634, 2021). "In animal models, REST mRNA and protein levels are consistently upregulated following induced status-epilepticus or ischemia." (PMID 33813634, 2021). "De-repression of REST in neurons has also been shown to occur in response to ischemia, leading to down-regulation of REST target genes, notably the GRIA2 subunit of the glutamate receptor regulating Ca2+ permeability and miR-29c, that promoted neuronal death." (PMID 28286748, 2017). "Impaired BBB and BCSFB function may lead to hypoplasticity through impairments in their physiological role in glucose transport, capillary perfusion, and neurogenesis, and possibly also by increasing REST signaling, which can be triggered by ischemia." (PMID 35346299, 2022). "The same year, the group identified miR-132 as a target of REST in ischemia." (PMID 33813634, 2021). "In addition, the neuron-specific miR-132 was a REST target mediating neuronal death upon ischemia." (PMID 37892159, 2023). "Therefore, like in ischemia and SE models, it seems likely that REST would be strongly upregulated following TBI, which could contribute to neuronal death and encourage seizure activity." (PMID 33813634, 2021). "In addition, the repression of miR-132 was selectively induced in vulnerable CA1 neurons, but not in CA3 neurons, supporting that REST-dependent repression of miR-132 is critical to ischemia-induced neuronal death." (PMID 25821444, 2015).
Down syndrome (10 papers, 2010 to 2025). "During early development, the loss of REST induces global hypermethylation, and the deregulation of REST was found to be an early event in Down syndrome (DS)." (PMID 37892159, 2023). "We previously showed that DYRK1A interacts with the REST/NRSF-SWI/SNF chromatin remodeling complex to deregulate gene clusters involved in the neuronal phenotypic traits of Down syndrome." (PMID 40003558, 2025). "To further explore the biological process function and mechanism involved in the role of REST in Down syndrome, we performed GO and KEGG enrichment analyses based on the REST-targeted DEGs using DAVID web tools." (PMID 37373133, 2023). "In this study, we identified and investigated the role of REST-target genes in human brain tissues, cerebral organoids, and neural cells in Down syndrome." (PMID 37373133, 2023). "In the context of NDD, Down’s Syndrome cells have increased expression of DYRK1A which leads to reduced NRSF/REST and misregulation of neurodevelopmental genes." (PMID 36216811, 2022).
brain tumors (9 papers, 2009 to 2025). "The DNA methylation aberrations found at NRSE regions may agree with a distinct REST dysregulation mechanism in brain and non-brain tumours given the opposite REST expression level and the presence of REST splice variants." (PMID 37301955, 2023). "Altered REST expression is not only found in mental disorder, neurobehavioral disorders 17-19 and ischemic stroke 20, but also found to be highly correlated with brain tumors." (PMID 39430242, 2024). "REST is a regulator of neuronal differentiation genes and has been mostly investigated in this context during normal brain development and brain tumors." (PMID 29435175, 2018). "Here we employed an integrated genomic approach to characterize REST activity and investigate its relevance to therapeutic targeting in brain tumors." (PMID 27698411, 2016). "Interestingly, we found that the clusters containing the majority of the pediatric brain tumors (Clusters 2/3, 4, and 5; α, ß, and Γ respectively) had significant differences in the expression patterns of LSD1, REST, and USP7." (PMID 30227871, 2018). "That this may indeed be the case is suggested by our observation that REST analyses of tumor samples we found that REST expression is extremely low to absent in control brain stem sections obtained from patients that did not have a brain tumor." (PMID 29435175, 2018). "These included REST and SIN3A, which inhibit neural differentiation and whose binding sites in PSCs, but not those in “other brain and neural samples” or “other brain tumors,” were enriched in MB-hyper regions." (PMID 38499326, 2024).
hearing loss (9 papers, 2021 to 2026). "REST expression was decreased in hair cells and spiral ganglion neurons in age-related hearing loss in mice." (PMID 36509837, 2023). "Later, a variant in a conserved intronic region of REST was found in a pedigree analysis to co-segregate with hearing loss." (PMID 36936679, 2023). "To investigate whether downregulation of REST causes hearing impairment, we performed conditional null deletion of Rest in SGNs and HCs." (PMID 35418568, 2022). "Heterozygous deletion of exon 4 resulted in the gain of function of REST, leading to HC degeneration and deafness, which is associated with DFNA27 hearing loss, suggesting that Rest4 is necessary for HC development and hearing." (PMID 36125121, 2022). "A recent study reported that the exon 4-containing REST splice variant (Rest4) is expressed in cochlear HCs and that its deletion results in abnormally high REST expression and is associated with DFNA27 hearing loss." (PMID 36125121, 2022). "In humans, a REST variant, which inhibits the splicing event of REST exon 4, was found in patients of a family (LMG2) with an inherited dominant form of postlingual progressive hearing loss." (PMID 37759701, 2023). "A gain‐of‐function effect seems unlike as studies in mice reported that downregulation of REST contributed to hearing impairment." (PMID 40605398, 2026). "Both the variants identified in the patient within the REST and SCD5 genes have never been characterized or directly associated with hearing loss and are classified as VUS according to the ACMG guidelines." (PMID 40121402, 2025).
cognitive decline (8 papers, 2016 to 2024). "CHD2 has previously been reported to interact with repressor element 1-silencing transcription factor (REST), which plays an important role in cognitive decline associated with AD34." (PMID 34011927, 2021). "Recent studies have further highlighted the essential role of REST in healthy aging and implicated that dysregulation of REST is associated with cognitive decline and AD." (PMID 31165472, 2019). "In this data set, we independently confirmed the strong association of REST with other candidate plasma proteins of cognitive decline at baseline: BDNF (r=0.5, P<0.001), RANTES (r=0.421, P=0.002) and PAI-1 (r=0.321, P=0.026)." (PMID 28585932, 2017). "Dysregulation of REST provides an insight into the underlying processes leading to AD by which aging factors in the brain lead to cognitive decline." (PMID 28585932, 2017). "Conversely, the REST-mediated response is lost in association with cognitive decline and AD." (PMID 37919281, 2023). "In the aging brain, the role of the so-called “repressor element silencing transcription factor” (REST), which is well known to initiate a specific “stress-response program”, has been highlighted to be preventive for cognitive decline and AD." (PMID 37189768, 2023). "This study aimed to 1) examine plasma REST levels and REST gene levels in AD patients and 2) further explore the pathological relationships between REST protein levels and cognitive decline in clinical conditions, including medial temporal lobe atrophy." (PMID 35650520, 2022). "We find that in both AD mouse models, genetic inactivation of REST accelerates cognitive decline." (PMID 37919281, 2023). "Deletion of REST in the 3xTg and J20 AD mouse models accelerates Aβ deposition and the accumulation of misfolded and phosphorylated tau, leading to neurodegeneration and cognitive decline." (PMID 37919281, 2023). "The main purpose of this study was to investigate whether REST protein and gene levels differ between participants with normal cognition and those with AD and whether the REST protein level is correlated with cognitive decline and medial temporal lobe atrophy." (PMID 35650520, 2022).
schizophrenia (8 papers, 2015 to 2025). A major psychotic disorder characterized by abnormalities in the perception or expression of reality. "This reveals a broad molecular interaction between H3K9 demethylation, NSRF/REST regulation and risk for ID and Schizophrenia." (PMID 36216811, 2022). "Significantly, the EHMT1-regulated miRNA gene set not only controls NRSF/REST but is enriched for association for Intellectual Disability (ID) and schizophrenia." (PMID 36216811, 2022). "The REST gene is related with not only neurodevelopmental such as ADHD but also it is associated with ASD, psychiatric disorder such as bipolar disorder and schizophrenia." (PMID 37518996, 2023). "Analysis of the EHMT1-regulated miRNA expression profile, including miR-153, miR-26a and miR-142, indicates a broader association between EHMT1 regulated miRNA, NRSF/REST and both ID and schizophrenia." (PMID 36216811, 2022). "This analysis suggests a broad association of a miRNA-mediated NRSF/REST regulatory pathway and psychiatric risk, particularly for a diagnosis of ID and schizophrenia." (PMID 36216811, 2022). "Work in various transgenic mouse models showed that DYRK1A binds SWI/SNF, the chromatin-remodeling complex regulated by REST, and is also involved in the pathogenesis of schizophrenia." (PMID 26465007, 2015). "In addition, SMARCA2—the catalytic ATPase subunit of SWI/SNF—has been found to interact with the REST/NRSF complex and other schizophrenia risk genes." (PMID 40160416, 2025). "Furthermore, the five NRSF/REST targeting miRNA associated with ASD were present in both ID and schizophrenia overlaps, giving a core miRNA gene set of miR-26a, miR-26b, miR-153, miR-181a and miR-548." (PMID 36216811, 2022). "Of the up-regulated miRNA gene sets that are known NRSF/REST regulators, there was significant enrichment for those associated with ID (all 11 miRNA) and schizophrenia (10 of 11 miRNA), but not ASD (5 of 11 miRNA)." (PMID 36216811, 2022). "REST can regulate the SMARCA4 gene and is linked to schizophrenia." (PMID 32039697, 2019). "Importantly it also reveals the presence of a more extensive pathway centred around NRSF/REST regulation of the neurodevelopmental gene regulation programme, which has broader significance for neurodevelopmental and psychiatric disorders, such as ID and schizophrenia." (PMID 36216811, 2022).
Wilms tumor (8 papers, 2018 to 2025). An embryonal neoplasm characterized by the presence of epithelial, mesenchymal, and blastema components. "Mutations in REST predispose to the Wilms tumor (the most common form of childhood renal cancer), suggesting that the gene acts as a tumor suppressor in this pediatric cancer." (PMID 33426787, 2021). "Mutations in the REST predispose to Wilms tumor, which accounts for ∼2% of Wilms tumor." (PMID 36130284, 2022). "REST is a master transcription repressor of neuronal genes and a proposed tumor suppressor in several malignancies like Wilms Tumor, triple negative breast cancer and small cell lung cancer." (PMID 40410286, 2025). "Our study identified TRIM28 as a major Wilms tumour predisposition gene, making a similar contribution to familial and unselected Wilms tumour as those of constitutional WT1 and REST mutations." (PMID 30885698, 2019).
diabetes (7 papers, 2012 to 2023). "This was confirmed in another line of RIP-REST animals featuring higher levels of REST transgene expression, which developed diabetes due to a dramatic loss in beta-cell mass." (PMID 28286748, 2017). "In fact, transfection of the N50-REST cDNA into MRC5 cells modifies the expression profiles of the REST target genes RRAD (Ras-related associated with diabetes) and TMS-1 (target of methylation induced silencing-1)." (PMID 22792276, 2012). "Despite the neuro-beneficial role of REST in aging, a recent study showed elevated REST in diabetes-induced mouse neurons, and REST knockdown averted the senescence that was brought on by diabetes." (PMID 37326903, 2023). "Mis-expression in adult beta cells using an inducible transgene PDX-tTA; TetO-REST also led to diabetes, as a combined effect of REST mis-expression over both differentiation and maintenance of beta cells." (PMID 28286748, 2017). "Although REST mutations and deregulation have yet to be connected to diabetes in humans, REST activation during both development and in adult beta cells leads to diabetes in mice." (PMID 28286748, 2017). "REST expression is forbidden in pancreatic endocrine cells and violation of this disallowance can provoke diabetes in mice." (PMID 28286748, 2017). "Specifically, we show here that high chronic levels of REST in beta cells leads to diabetes, due to prolonged repression of multiple REST-target genes known to contribute to beta cell survival." (PMID 23029270, 2012). "We now document a role for REST target genes in beta cell survival in a RIP-REST mouse line which displayed diabetes, as a result of a high level of REST expression, which was associated with a massive loss of adult beta cells." (PMID 23029270, 2012). "Though REST gain-of-function mutations have not yet been reported as causes of monogenic diabetes, the 22 known mutations account for 80% of cases." (PMID 28286748, 2017).
frontotemporal dementia (7 papers, 2009 to 2022). Frontotemporal dementia (FTD) comprises a group of neurodegenerative disorders, characterized by progressive changes in behavior, executive dysfunction and language impairment, as a result of degeneration of the medial prefrontal and frontoinsular cortices. "In addition, early stage AD brains showed higher expression of REST target genes, while late stage AD and frontotemporal dementia (FTD) brains showed lower expression." (PMID 25250042, 2014).
colon cancer (6 papers, 2010 to 2025). "In contrast, loss of functional REST expression through genetic mutations has been shown to contribute to colon cancer progression." (PMID 22496669, 2012). "In one of these studies, it was observed that decreasing REST levels in colon cancer cells increased Akt phosphorylation, a relevant factor that leads cells to proliferate." (PMID 38542313, 2024). "Similar to our results, the REST gene, identified as a tumor suppressor by using an shRNA library, is in a frequently deleted chromosomal location in colon cancer." (PMID 27323405, 2016). "Also, for colon cancer a tumor suppressing function was described where a reduced REST expression resulted in enhanced activity of the PI3K/AKT/mTOR signaling pathway, the target of Everolimus, a main therapeutic agent in siNET treatment." (PMID 40410286, 2025). "Similarly, reintroduction of full-length REST into REST–less colon cancer cell lines restores anoikis, blocking anchorage-independent cell growth." (PMID 20548947, 2010). "Importantly, the IHC staining for REST C-terminus has the ability to identify tumors that have lost full-length REST via multiple mechanisms, including REST4 splicing, ubiquitin-mediated degradation or truncating mutation, as has been seen in colon cancer." (PMID 20548947, 2010). "REST4 and the truncated form of REST identified as a SNP in colon cancer are not recognized by this antibody, allowing us to identify tumors that lack full-length REST." (PMID 20548947, 2010).